GEMIN5 (gem nuclear organelle associated protein 5)
Description:
The SMN complex catalyzes the assembly of small nuclear ribonucleoproteins (snRNPs), the building blocks of the spliceosome, and thereby plays an important role in the splicing of cellular pre-mRNAs. Most spliceosomal snRNPs contain a common set of Sm proteins SNRPB, SNRPD1, SNRPD2, SNRPD3, SNRPE, SNRPF and SNRPG that assemble in a heptameric protein ring on the Sm site of the small nuclear RNA to form the core snRNP (Sm core). In the cytosol, the Sm proteins SNRPD1, SNRPD2, SNRPE, SNRPF and SNRPG are trapped in an inactive 6S pICln-Sm complex by the chaperone CLNS1A that controls the assembly of the core snRNP. To assemble core snRNPs, the SMN complex accepts the trapped 5Sm proteins from CLNS1A forming an intermediate. Binding of snRNA inside 5Sm ultimately triggers eviction of the SMN complex, thereby allowing binding of SNRPD3 and SNRPB to complete assembly of the core snRNP. Within the SMN complex, GEMIN5 recognizes and delivers the small nuclear RNAs (snRNAs) to the SMN complex. Binds to the 7-methylguanosine cap of RNA molecules (PubMed:19750007, PubMed:27834343, PubMed:27881600, PubMed:27881601, Ref.27). Binds to the 3'-UTR of SMN1 mRNA and regulates its translation; does not affect mRNA stability. May play a role in the regulation of protein synthesis via its interaction with ribosomes.
Synonyms: GEMIN-5; NEDCAM
Tractability: Small molecule: a structure with a bound ligand is known. PROTAC: UniProt records ubiquitination sites on it; ubiquitination databases record sites on it; its protein half-life has been measured.
Gene: Protein-coding gene on chromosome 5 (154,887,411 to 154,938,211, reverse strand). Ensembl gene ENSG00000082516.
Subcellular location: Nucleus, nucleoplasm; Nucleus, gem; Cytoplasm
Subcellular location (Human Protein Atlas): Cytosol; Nuclear bodies
Pathways (Reactome):
Disease: SARS-CoV-2 modulates host translation machinery
Metabolism of RNA: snRNP Assembly
Gene Ontology:
Molecular function: mRNA 3'-UTR binding; protein binding; ribosome binding; RNA 7-methylguanosine cap binding; RNA binding; snRNA binding; U1 snRNA binding; U4 snRNA binding; U4atac snRNA binding
Biological process: regulation of translation; spliceosomal snRNP assembly; mRNA splicing, via spliceosome; protein-containing complex assembly
Cellular component: cytoplasm; cytosol; membrane; nuclear body; nucleoplasm; SMN complex; SMN-Gemin2 complex; SMN-Sm protein complex; nucleus; Gemini of Cajal bodies
Genetic constraint (gnomAD): Loss-of-function variants: 78 observed, 112.3 expected, observed/expected ratio (o/e) 0.69, 90% interval 0.58 to 0.84. The upper end of that interval is the gene's LOEUF score, 0.84, which puts it in group 3 of 6, group 1 being the genes least tolerant of losing a copy. Missense variants: 1,279 observed, 1,276.4 expected, observed/expected ratio (o/e) 1, 90% interval 0.96 to 1.05. Synonymous variants: 469 observed, 489.09 expected, observed/expected ratio (o/e) 0.96, 90% interval 0.89 to 1.03.
Gene-disease validity (ClinGen):
ClinGen rates the evidence that GEMIN5 causes each of these diseases.
neurodevelopmental disorder with cerebellar atrophy and motor dysfunction (autosomal recessive): Definitive.
Homologues: Orthologues: chimpanzee GEMIN5 (99% identical), macaque GEMIN5 (98% identical), rabbit GEMIN5 (89% identical), pig GEMIN5 (89% identical), dog GEMIN5 (89% identical), guinea pig GEMIN5 (83% identical), mouse Gemin5 (82% identical), rat Gemin5 (82% identical), tropical clawed frog gemin5 (56% identical), zebrafish gemin5 (51% identical). Paralogues in human: WDR59 (11% identical), WDR24 (9% identical), RBBP4 (6% identical), WDR77 (6% identical), RBBP7 (6% identical), PEX7 (5% identical), GRWD1 (5% identical), WDR73 (5% identical), ERCC8 (5% identical).
Diseases named in the same sentence as GEMIN5 in open-access papers:
GEMIN5 is named in the same sentence as 29 diseases in open-access papers, as found by Europe PMC text mining. Sharing a sentence is not in itself a finding about the gene and the disease. The quoted sentences say what the papers report.
Cerebellar atrophy (6 papers, 2021 to 2025). Cerebellar atrophy is defined as a cerebellum with initially normal structures, in a posterior fossa with normal size, which displays enlarged fissures (interfolial spaces) in comparison to the foliae secondary to loss of tissue. "Biallelic variants in GEMIN5 are also known to cause developmental delay, motor dysfunction, and cerebellar atrophy." (PMID 39858526, 2025). "Defects in GEMIN5 are associated with cerebellar atrophy, intellectual disability, movement disorders, and early infantile developmental epileptic encephalopathy (EIDEE)." (PMID 39858526, 2025). "Several biallelic truncating and missense variants of the gem nuclear organelle–associated protein 5 (GEMIN5) gene have been reported to cause neurodevelopmental disorders characterized by cerebellar atrophy, intellectual disability, and motor dysfunction." (PMID 38773790, 2024). "Here, we describe the identification of biallelic variants in the GEMIN5 gene among seven unrelated families with nine affected individuals presenting with spastic ataxia and cerebellar atrophy." (PMID 35295849, 2022). "Although these findings are interesting, we are unable to establish a link between cerebellar atrophy and Gemin5 loss of function due to early embryonic lethality in our knockout Gemin5 mice." (PMID 35295849, 2022). "Our work further expands on the phenotypic spectrum associated with GEMIN5-related disease and implicates the role of GEMIN5 among patients with spastic ataxia, cerebellar atrophy, and motor predominant developmental delay." (PMID 35295849, 2022). "In summary, we have shown that biallelic variants in GEMIN5 cause developmental delay, motor dysfunction, and cerebellar atrophy and reduce snRNP complex assembly proteins, impair snRNP assembly and misregulate RNA targets." (PMID 33963192, 2021). "Here we describe the clinical and molecular spectrum of variants in GEMIN5 among 30 patients presenting with developmental delay, hypotonia, motor dysfunction, and cerebellar atrophy, suggesting that GEMIN5 variants give rise to a distinct clinical phenotype." (PMID 33963192, 2021). "We identified biallelic variants in GEMIN5 that give rise to a neurological syndrome which features developmental delay, cerebellar atrophy, and predominant motor dysfunction along with hypotonia." (PMID 33963192, 2021). "Fully consistent with this hypothesis, Gemin5 biallelic variants have been recently associated with cerebellar atrophy and spastic ataxia in several human patients." (PMID 35393353, 2022). "Bi-allelic truncating and missense variants in GEMIN5 have been associated with NEDCAM syndrome, a neurodevelopmental condition characterized by cerebellar atrophy, ID, and motor dysfunction." (PMID 36980979, 2023). "Given the distinct neurological presentation, we propose the term GEMIN5-related neurodevelopmental ataxia with cerebellar atrophy to describe the variability in clinical presentation associated with this gene." (PMID 35295849, 2022). "We think it would be worth considering testing for GEMIN5 variants in SMN1 negative neonates with severe hypotonia and absent reflexes, especially with cerebellar atrophy on imaging." (PMID 33963192, 2021).
cerebellar ataxia (4 papers, 2021 to 2025). A neurological syndrome characterized by clumsy and uncoordinated movement of the limbs, trunk, and cranial muscles. "Patients carrying GEMIN5 biallelic variants display neurodevelopmental delay, hypotonia, and cerebellar ataxia." (PMID 40176294, 2025). "Patients carrying GEMIN5 biallelic variants suffer from neurodevelopmental delay, hypotonia, and cerebellar ataxia." (PMID 40176294, 2025). "On the other side, biallelic mutations in GEMIN5 have recently been linked to early-onset neurodevelopmental delay and ataxia." (PMID 36136249, 2022). "We, hence, categorize the neurological phenotype associated with autosomal recessive variants in GEMIN5 as predominantly in the hereditary cerebellar ataxia–spastic paraplegia spectrum of disease." (PMID 35295849, 2022). "We focused on specific candidates: ATXN2, whose polyQ expansions cause spinocerebellar ataxia 2 (SCA2), and GEMIN5, whose biallelic mutations cause neurodevelopmental delay and ataxia." (PMID 36136249, 2022). "Here, we have identified 30 affected individuals from 22 unrelated families presenting with developmental delay, hypotonia, and cerebellar ataxia harboring biallelic variants in the GEMIN5 gene." (PMID 33963192, 2021).
developmental delay (3 papers, 2021 to 2024). "Patients 1 and 2 share core GEMIN5 variant features like cerebellar hypoplasia and developmental delay." (PMID 38773790, 2024). "We have previously shown that genetic reduction of endogenous rigor mortis (fly homolog of human GEMIN5) leads to developmental delay, motor dysfunction, and reduced lifespan, similar to human patients with autosomal recessive variants in GEMIN5." (PMID 35295849, 2022). "Conditional ubiquitous RNA-mediated knock down of endogenous rigor mortis in Drosophila caused severe developmental defects, premature lethality, motor dysfunction, and reduced life span, similar to our patients with GEMIN5 variants showing motor predominant developmental delays." (PMID 33963192, 2021).
spinal muscular atrophy (3 papers, 2022 to 2024). A motor neuron disease that affect the muscles, and characterized by muscle weakness and atrophy resulting from progressive degeneration and irreversible loss of the anterior horn cells in the spinal cord (i.e., lower motor neurons) and the brain stem nuclei. "Furthermore, this GEMIN5 neurodevelopmental ataxia spectrum is characteristically distinct from the predominantly neuromuscular presentation of spinal muscular atrophy (SMA) caused by another member of the SMN protein complex." (PMID 35295849, 2022). "Previous studies have shown that GEMIN5 can stimulate translation of the survival of motor neuron (SMN) mRNA, and decreased levels of SMN protein can cause muscle diseases such as spinal muscular atrophy." (PMID 37206976, 2023).
viral infection (2 papers, 2020 to 2025). "The protein is redistributed to the viral factories, co‐localizing with SINV RNA and various viral proteins, indicating a specific GEMIN5 response to viral infection." (PMID 40176294, 2025). "Currently, whether Gemin5 performs a critical role in other virus infections remains an open question." (PMID 32485878, 2020). "Regarding the role of Gemin5 in the regulation of gene expression under severe stress as it occurs during viral infections, it has been shown that the protein is redistributed to the viral factories during Sindbis virus (SINV) infection co-localizing with SINV RNA." (PMID 32485878, 2020).
breast carcinoma (1 paper, 2021). "It has been reported that GEMIN5 was the most differentially varied protein in breast cancer cell lines after modulation of Nm23-H1, which is the first MSG to be characterized." (PMID 35096829, 2021).
Cerebral atrophy (1 paper, 2023). Atrophy (wasting, decrease in size of cells or tissue) affecting the cerebrum. "Here, we report a homozygous 3bp-deletion variant in GEMIN5 in three siblings born from consanguineous parents presenting with ID, cerebral atrophy, walking and speaking impairment, and motor dysfunctions." (PMID 36980979, 2023).
developmental and epileptic encephalopathies (1 paper, 2024). "Here, we reported two patients harboring biallelic variants in the GEMIN5 gene and suffering from early‐infantile developmental and epileptic encephalopathies (EIDEE), but otherwise presenting with clinical features distinct from NEDCAM syndrome, broadening the phenotypic spectrum of GEMIN5." (PMID 38773790, 2024).
epilepsy (1 paper, 2024). A brain disorder characterized by episodes of abnormally increased neuronal discharge resulting in transient episodes of sensory or motor neurological dysfunction, or psychic dysfunction. "In conclusion, we found novel biallelic variants of GEMIN5 in two individuals with EIDEE, dysgenesis of the corpus callosum and drug‐resistant epilepsy, which expands the phenotypes and increases awareness of the association between GEMIN5 variants and epilepsy." (PMID 38773790, 2024).
epileptic encephalopathies (1 paper, 2024). "However, the association between biallelic GEMIN5 variants and early‐infantile developmental and epileptic encephalopathies (EIDEEs) has not been reported." (PMID 38773790, 2024).
Motor Neuron Disease (1 paper, 2024). "Indeed, SMN gene alterations lead to a motor neuron disease, whereas GEMIN5 mutations cause neurodevelopmental diseases." (PMID 39337533, 2024). "Our study reveals GEMIN5 regulates Kdm6b expression with implications for motor neuron diseases and therapy." (PMID 39337533, 2024). "In conclusion, our study reveals the RNA-binding protein GEMIN5 to regulate Kdm6b gene expression with implications for motor neuron diseases and therapy." (PMID 39337533, 2024). "Beyond motor neuron disease mechanisms, it reveals a role for GEMIN5 in the regulation of the epigenetic enzyme KDM6B expression and consequently, enabling the expression of KDM6B-Isl1-Lxh3 target gene HB9, which consolidates motor neuron identity." (PMID 39337533, 2024).
tumor (11 papers, 2020 to 2022). "Gem Nuclear Organelle Associated Protein 5 (GEMIN5), a component of the spliceosomal complex, plays a crucial role in mRNA splicing and can affect tumor cell motility." (PMID 35096829, 2021). "For instance, analyze the global mRNA splicing profile of the MDA-MB-435 tumor cell line at metastatic state or suppression state, showing a distinct splicing profile between different cellular states in dependence on Gemin5." (PMID 33996826, 2021). "High GEMIN5 expression was significantly correlated to tumor size (p = 0.031), T-stage (p = 0.009), lymphatic metastasis (p = 0.001), TNM stage (p = 0.002) and histological grade (p = 0.034)." (PMID 35096829, 2021). "GEMIN5 codes Gemin5; alteration of GEMIN5 expression may play a role in alternative mRNA splicing and tumor cell motility." (PMID 33133141, 2020). "Gemin5 may participate in tumor cell motility through the alternative splicing process." (PMID 33996826, 2021). "The 5hmC levels and gene expression of BMS1 and GEMIN5 are both reduced in AML compared to controls, supporting the tumor suppressor nature of these genes." (PMID 35859008, 2022). "In our study, we found high expression of EIF4E1B, LARP1, GEMIN5, and DCP2 in tumor tissues, which seems to be consistent with our results." (PMID 36003341, 2022). "Similar results were found for GANAB vs. GEMIN5, both of which are located within G3BP1 genomic loci and also driven by copy number alterations in tumor." (PMID 35879690, 2022). "Lastly, 10 paired CRC tumor and paracancerous tissue samples were obtained, and qRT-PCR analyses revealed that EIF4E3 and GEMIN5 were downregulated in CRC, whereas NCBP2 was upregulated." (PMID 36482181, 2022). "The expression of CNV-amplified m7G regulators was markedly higher in HCC specimens than in normal control specimens, such as AGO2, NCBP2, GEMIN5 and LARP1, while the expression of EIF4E3 was significantly lower in tumor specimens." (PMID 36389726, 2022).
cancer (9 papers, 2009 to 2025). A tumor composed of atypical neoplastic, often pleomorphic cells that invade other tissues. "In line with the potential implication of GEMIN5 in cancer progression, this protein was also identified as a mediator of m6A modification of mRNA, enhancing translation via eIF3 translation initiation complex recruitment in pancreatic cancer." (PMID 40176294, 2025). "We found that the expression of GEMIN5 was higher in the tissues of patients with HCC than in normal tissues adjacent to cancer and that patients with high expression had a poor prognosis." (PMID 35620469, 2022). "Concerning additional functions of GEMIN5 related to protein synthesis, recent data reported the identification of this protein together with other RBPs and eIFs in the list of m7G‐binding proteins related to the progression of several cancers." (PMID 40176294, 2025).
neurodevelopmental disorder (7 papers, 2021 to 2024). A behavioral and cognitive disorder with onset during the developmental period that involves impaired or aberrant development of intellectual, motor, or social functions. "More importantly, Gemin5 variants were recently linked with human neurodevelopmental disorders, perturbing distinct pathways as compared with defects in the SMN protein." (PMID 35393353, 2022). "Here, we sought to establish the impact of Gemin5 missense variants found in compound heterozygosity in patients developing neurodevelopmental disorders." (PMID 35393353, 2022). "Here, we report functional and structural deficiencies associated with compound heterozygosity variants within the Gemin5 gene found in patients with neurodevelopmental disorders." (PMID 35393353, 2022). "Here, the authors identify loss of function mutations in GEMIN5 that are associated with a human neurodevelopmental disorder." (PMID 33963192, 2021). "Therefore, we are tempted to suggest that neurodevelopmental disorders mediated by Gemin5 pathogenic mutations placed on its C-terminal region (G5C) are likely associated with aberrant mRNA binding." (PMID 36056043, 2022). "GEMIN5 mutations could therefore perturb histone marks and, consequently, the progression of gene programs during embryonic and postnatal development, triggering a neurodevelopmental disorder." (PMID 39337533, 2024). "Recent studies have shown that loss of function of Gemin5 is detrimental for cell survival, and mutant forms of the protein showing failures in RNA-binding, protein–protein interactions, and ribosome association were found in patients with human neurodevelopmental disorders." (PMID 35987821, 2022). "Brain abnormalities are the most common clinical manifestation of GEMIN5‐related neurodevelopmental disorders." (PMID 38773790, 2024).
neurological diseases (4 papers, 2020 to 2025). "This reinforces the crucial role of the GEMIN5 gene in the nervous system and the potential for its mutation to be a factor in the onset of neurological diseases." (PMID 38773790, 2024). "Soon after the reports defining functional and structural domains of the protein were published, it became clear that mutations in the GEMIN5 gene detected in patients with neurological disorders could be detrimental." (PMID 40176294, 2025). "The exome sequencing of three patients with neurological disorders revealed the presence of biallelic variants within Gemin5, absent in the normal population (GnomAD database)." (PMID 35393353, 2022).
hematopoietic diseases (1 paper, 2021). "At last, it is worth identifying whether there are human hematopoietic diseases caused by Gemin5 mutations and what extent of Gemin5 involved in human diseases in blood system." (PMID 33996826, 2021).
infection (1 paper, 2018). The state of being infected such as from the introduction of a foreign agent such as serum, vaccine, antigenic substance or organism. "Interestingly, Gemin5 cleavage by Lpro was only observed in FMDV-infected cells but not during infection with picornaviruses belonging to different genera like SVDV or EMCV." (PMID 29958302, 2018).
GEMIN5 also shares sentences with these, for which no sentence is quoted: colorectal cancer (2 papers); glioma (2); spastic ataxia (2); Ataxia (1); Cerebellar hypoplasia (1); gastric cancer (1); Intellectual disability (1); melanoma (1); neurodegenerative disease (1); Neurodevelopmental delay (1); Spastic paraplegia (1); spinocerebellar ataxia 2 (1).